RUNX1 (RUNX family transcription factor 1)
Diseases named in the same sentence as RUNX1 in open-access papers (continued):
Sharing a sentence is not in itself a finding about the gene and the disease.
tumor (continued). "It highlights the versatility of Runx1 as a potential tumor regulator, engaging in processes that directly influence OS aggressiveness and therapeutic response." (PMID 40989695, 2025). "This would be due to the differentiation function of PHF6 and RUNX1, and the tumor-suppressive function of PHF6." (PMID 38418452, 2024). "The results showed that Runx1 OE significantly promoted the tumor growth in vivo, while tumors in CT2A-shRunx1-implanted mice exhibited retarded growth rates, compared with the respective control mice." (PMID 38286983, 2024). "Aberrant over-expression of RUNX1 has been noted in various cancer types, suggesting both oncogenic and tumor-suppressive roles." (PMID 39309442, 2024). "Overall, RUNX3 predominantly acts as a dampener of tumor stemness, distinguishing it from RUNX1 and RUNX2." (PMID 38430423, 2024). "To explore the recruitment of TAMs in CRC tissue possibly related to RUNX1, we collected 66 pairs of fresh tumor specimens with matched normal tissues from CRC patients in our hospital." (PMID 38419056, 2024). "We found that Runx1 was dramatically up‐regulated in the tumor‐infiltrating cells of NSCLC in contrast to its low expression in the normal lung tissues." (PMID 37967345, 2024). "Considering RUNX1's enhancement of CRC cell migration and invasion in vitro, the study subsequently assessed RUNX1's impact on tumor growth and metastasis in vivo." (PMID 39309442, 2024). "Overall, the data indicates that RUNX1's regulatory role in tumor stemness varies in a cancer subtype-specific manner." (PMID 38430423, 2024). "Studies suggest RUNX1 promotes migration and proliferation, indicating its potential tumor-suppressive function." (PMID 39201328, 2024). "In conclusion, our data suggest that RUNX1 promotes CRC angiogenesis by regulating M2 macrophages during the complex crosstalk between tumor cells and TAMs." (PMID 38419056, 2024). "We thus aimed to investigate the RUNX1 mediated crosstalk between tumor cells and M2 TAMs in CRC, and its relationship with neoplastic angiogenesis." (PMID 38419056, 2024). "The RUNX1 (RUNX family transcription factor 1) transcription factor is a tumor suppressor in the mammary epithelium, and ts-112 is confirmed to have carcinogenic potential." (PMID 38577588, 2024). "In overall, our results uncovered a new pathogenic role of Runx1 in MMT development, representing a novel druggable target for the development of targeted therapy against the MMT‐driven formation of tumor‐promoting CAFs in clinical NSCLC." (PMID 37967345, 2024). "Conversely, upon overexpression of RUNX1, both tumor volume and weight exhibited a notable increase in comparison to the control group." (PMID 39309442, 2024). "In an osteosarcoma study, the expression levels of RUNX1 mRNA and protein were found to be higher in tumor tissues than in normal tissues adjacent to the tumor." (PMID 38430423, 2024). "To determine if the genomic binding of HA-tagged RUNX1::RUNX1T1 is altered due to the loss of Mga, we performed CUT&RUN on GFP+ sorted tumor cells isolated from the spleen." (PMID 38454121, 2024). "Throughout the observation duration, the growth curve indicated a marked increase in tumor volume for the RUNX1-overexpressing cells relative to the control, an elevation considerably diminished upon MUC13 suppression." (PMID 39309442, 2024). "To identify the chromatin occupancy of RUNX1 in GBM tumor cells, we performed chromatin immunoprecipitation (ChIP) followed by sequencing (ChIP-seq) analysis in N9 cells stably infected with lentivirus carrying shRNA targeting RUNX1 or shVector." (PMID 38286983, 2024). "To address the molecular characteristics of tumor-reactive T cells in AML with RUNX1::RUNX1T1, we compared the transcriptional regulon and gene expression profile between tumor-reactive T cells and bystander T cells." (PMID 39243082, 2024).
tumor (continued). "RUNX1, identified as a critical transcription factor, has been observed to regulate circRNAs expression, consequently influencing tumor progression." (PMID 38956466, 2024). "Our results showed that RUNX1 derived from tumor cells recruits TAMs cells and induces macrophage polarization into the M2 state by promoting the secretion of CCL2 and the activation of Hedgehog signaling pathway." (PMID 38419056, 2024). "Consistent with these biostatistics and the previous study 32, RUNX1 was significantly elevated in tumor tissues relative to levels in the corresponding adjacent non-tumor tissues." (PMID 39309442, 2024). "Conversely, RUNX1's tumor-suppressive role is notably crucial within the gastrointestinal tract, effectively reducing the incidence of tumorigenesis." (PMID 39309442, 2024). "Due to its established involvement in aggressive tumor characteristics, RUNX1's functions in CRC require further investigation to understand its potential as a therapeutic target." (PMID 39309442, 2024). "As expected, BA-treated tumours had reduced expression of TGF-β target genes (Thbs1, Vegfa, Runx1), as well as genes linked to ascites production (Vegfa)." (PMID 38622286, 2024). "IHC staining of both RUNX1 and Ki67 revealed that the tumor xenografts with elevated RUNX1 expression exhibited notably enhanced proliferation capacities, implying a crucial function of RUNX1 in promoting the growth of CRC." (PMID 39309442, 2024). "Surprisingly, by conducting unbiased bioinformatics with our macrophage lineage cells specific scRNA‐seq dataset, we detected a hematopoietic transcription factor Runx1 was highly expressed in the MMTs of LLC‐tumor in vivo." (PMID 37967345, 2024). "Based on the expression of RUNX1 in tumor tissues, the mice were divided into two groups: low RUNX1 (RUNX1low) and high RUNX1(RUNX1high)." (PMID 37697370, 2023). "In GBM, RUNX1 promotes the invasion of tumor cells, and correlates with the maintenance of the MES phenotype and poor prognosis of GBM patients." (PMID 36949071, 2023). "To clarify the link between USP10 and RUNX1 in GBM subtypes, we constructed a heatmap for the expression markers of GBM-associated tumor markers across GBM types." (PMID 36949071, 2023). "In PDAC, several studies have shown that RUNX1 plays an oncogenic role in tumor growth and metastasis." (PMID 37697370, 2023). "RUNX1 showed lower expression in breast tumor tissues than normal tissues and sharply company with the tumor malignancy increase." (PMID 38057816, 2023). "On the other hand, patient tumor samples with high YAP1 but low RUNX1 and RUNX3 depicted higher levels of gene signatures associated with EMT and cancer cell stemness." (PMID 36831308, 2023). "As illustrated in the heat maps, a negatively significant correlation was noted between RUNXs expression and the tumor purity in several tumor types; specifically in 19 tumor types for RUNX1, in 21 types for RUNX2, and in 23 types for RUNX3." (PMID 36321611, 2023). "Histologically, H&E staining showed that the USP10-overexpressing xenografts displayed rampant tumor growth, whereas this effect was reversed by inhibition of RUNX1." (PMID 36949071, 2023). "Macrophage infiltration was recorded in 22 tumor types for RUNX1, in 25 types for RUNX2, and in 18 types for RUNX3." (PMID 36321611, 2023). "Among them, RUNX1 was relatively more highly expressed than the other two RUNX genes, and the significant difference in RUNX1 expression between tumor and para-tumor tissues excluded the role of RUNX2 and RUNX3, suggesting the importance of abundant RUNX1." (PMID 37697370, 2023). "The details of PDAC patients from TCGA data were analyzed and RUNX1 expression of tumor tissues from PDAC patients grouped by response to GEM was compared." (PMID 37697370, 2023).
tumor (continued). "CD8+ T cell infiltration was recorded in 21 tumor types for RUNX1, in 18 types for RUNX2, and in 21 types for RUNX3." (PMID 36321611, 2023). "The role of RUNX1 in tumor metastasis has been examined in several studies, and its possible mechanism involves activating the Wnt/β−catenin signaling pathway and EMT." (PMID 36982956, 2023). "It has been reported that RUNX1 regulated tumor function by activating downstream STAT3 and transcriptionally regulating EGFR gene expression." (PMID 38057816, 2023). "CRISPR mediated knockout of IGF2BP1 or ETV6::RUNX1 led to reduced tumor cell survival and reversal of prednisolone resistance." (PMID 37670323, 2023). "A previous RUNX1 ChIP assay performed by our group in MDA-MB-231 cells revealed that RUNX1 binds to different tumor-related genes." (PMID 36766786, 2023). "IGF2BP1 expression was essential for tumor cell survival in multiple ETV6::RUNX1 positive B-ALL cell lines." (PMID 37670323, 2023). "In PDAC, RUNX1 has been identified as an oncogene in tumor growth and metastasis and the other roles and mechanisms of RUNX1 leading to the malignant progression of PDAC are not well known." (PMID 37697370, 2023). "A parallel analysis was performed in ESCC, which identified a number of tumor-specific factors, including RUNX1/3, SOX2/4, and CEBPA/B." (PMID 37620896, 2023). "RUNX family transcription factor 1 (RUNX1), a tumor suppressor, and RUNX2 have contradictory regulatory effects on EMT in BRCA." (PMID 38235137, 2023). "A previous study showed that the SE regulator CDK7 inhibitor THZ1 caused significant tumor regression in MYCN-amplified neuroblastoma cells and affected RUNX1 transcription in Jurkat T-ALL cells." (PMID 37501079, 2023). "For example, in ESCC, several SE-related oncogenes influence tumor proliferation, such as RUNX1, DNAJB1, and PAK4." (PMID 37501079, 2023). "We found that FOSB and RUNX1, as important drivers of tumour proliferation and invasion, were significantly associated with the OS of EOC patients and upregulated during EMT." (PMID 37817210, 2023). "More importantly, the RUNX1 inhibitor displayed a safe and promising effect in inhibiting tumor growth in GEM-resistant xenograft and PDX mouse models." (PMID 37697370, 2023). "In the case of AML1‐ETO AML, the RUNX1‐ETO fusion protein limits chromatin accessibility at the LOUP locus and causes inhibition of PU.1 expression, thus halting the tumor suppressor role of LOUP and causing differentiation block and increased proliferation." (PMID 37267628, 2023). "The alignment of the response assessment and RUNX1 staining showed that patients with disease progression exhibited strong staining for RUNX1 in tumor tissues; however, those with response to chemotherapy showed weak staining." (PMID 37697370, 2023). "The role of RUNX1 is still contradictory, as there are reports of its tumour-suppressive but also oncogenic role in HCC." (PMID 37759525, 2023). "Compared with vehicle-treated mice, tumor-bearing mice receiving Spautin-1 showed inhibited tumor formation and growth rate, which was reversed by RUNX1 overexpression." (PMID 36949071, 2023). "A significant positive correlation was noted between RUNXs expression and B cell infiltration in several tumor types; specifically, in 17 types for RUNX1, in 18 types for RUNX2, and in 21 types for RUNX3." (PMID 36321611, 2023). "The results of H&E staining indicated that the xenografts carrying USP10 shRNA LN229 and GBM2 cells displayed restricted tumor growth, whereas this effect was reversed by overexpression of RUNX1." (PMID 36949071, 2023).
tumor (continued). "Multivariate Cox regression analysis of covariates including clinical factors (such as age, gender, and tumor purity), immune infiltrates, and RUNXs expression also revealed that age and RUNX1 expression are independent prognostic factors." (PMID 36321611, 2023). "The role of RUNX1 as either a tumor suppressor gene or an oncogene is tissue-dependent and varies based on the cancer type." (PMID 36430923, 2022). "We therefore conducted further investigations of the anti-tumour effects of RUNX1 using the tetracycline-inducible short hairpin RNA (shRNA)-mediated RUNX1 knockdown system." (PMID 36085167, 2022). "In contrast, when tumor grade grew, RUNX1 expression in BLCA and BRCA declined, and RUNX3 expression in TGCT decreased." (PMID 35522574, 2022). "In this sense, these authors suggested that RUNX1 is a tumour suppressing factor that inhibits angiogenesis." (PMID 35740337, 2022). "To further ascertain the effect of RUNX1 on hepatocytes alterations, we used the tumour specimens that we previously generated from the intrahepatic xenograft mouse model." (PMID 35267627, 2022). "The role of RUNX1 in tumorigenesis is complex, acting as an oncogene or a tumor suppressor, depending on the tissue or even on the cell type within the same tissue." (PMID 36430923, 2022). "RUNX1 expression is reduced in solid tumors prone to metastasis, indicating its role in suppressing tumor progression." (PMID 36005134, 2022). "RUNX1 expression rose in the UVM as tumor grade increased, while RUNX2 expression increased in the STAD, ESCA, and KICH." (PMID 35522574, 2022). "The knockdown of RUNX1 in the cancer cells dramatically attenuated the infiltration of neutrophils into the tumour microenvironment (TME)." (PMID 36330498, 2022). "RUNX1 (runt-related transcription factor 1) is known as a tumor suppressor in hematopoietic malignancies." (PMID 35631574, 2022). "We investigated the consequences of SVs for RUNX1, using PCR to confirm the genomic junctions, in 69 sequenced tumours as well as in two OAC cell lines, FLO-1 and OE3341." (PMID 35396535, 2022). "The results showed that RUNX1 was expressed at a moderate level in tumor tissues, but very weak RUNX1 staining was detected in any normal tissue." (PMID 35534796, 2022). "Runt-related transcription factor-1 (RUNX1) is a transcription factor that is required for tumour progression and chemoresistance in various cancers." (PMID 36330498, 2022). "Although RUNX1 is generally considered to be a tumour suppressor, accumulated evidence reveals it plays a central role in leukemogenesis and can act as an oncogene as well." (PMID 36467848, 2022). "DNA was available for 17 tumours with a total of 22 RUNX1 SVs, and 20/22 (91%) were verified by PCR and Sanger sequencing, as were 3 SVs in the two cell lines." (PMID 35396535, 2022). "The downregulation of miR-9 is found to improve the differentiation of tumor MDSCs via targeting Runx1, thereby hindering tumor growth." (PMID 35359390, 2022). "It is also noteworthy that some RUNX1 mutants associated with breast cancer cannot be sumoylated through PIAS1, and that in sumoylation defective mutants of RUNX3 the tumor suppressor capacity is nullified, promoting tumor growth." (PMID 35887358, 2022). "Increased RUNX1 expression is strongly associated with HNSC, predicting tumor recurrence and patient prognosis." (PMID 35534796, 2022). "In CRC, for example, LRG1 has been shown to inhibit apoptosis and modulate the EMT of tumour cells through expression of the transcription factors RUNX1 and HIF-1α, whose association with TGFβ and contribution to tumour growth are well-established." (PMID 35062948, 2022). "Since iAMP21 tumours are defined by RUNX1 copy number, we examined the distribution of SVs on chromosome 21, finding no clustering evident." (PMID 34753926, 2021).
tumor (continued). "Runt-related transcription factor 1 (RUNX1), also known as acute myeloid leukemia 1, is a sequence-specific DNA-binding transcription factor that can act as an oncogene or tumor suppressor, depending on its interaction with specific co-regulatory proteins." (PMID 34063472, 2021). "This, alongside RUNX2 and RUNX1 cooperation in tumour cells and RUNX1 recruitment to the E-cad promoter, raises a possibility of similar recruitment of RUNX2, and therefore Rb, to the E-cad promoter." (PMID 34262912, 2021). "Low-risk group enrichment analysis showed that the enrichment of classic tumor signaling pathways such as the transcriptional regulation of RUNX1, interferon signal, Wnt and MAPK." (PMID 33758106, 2021). "In studies of CRC, RUNX1 regulates tumor metastasis by activating the Wnt/β-catenin signaling pathway and EMT." (PMID 34659526, 2021). "RUNX1 occupied thousands of genomic regions that corresponded to genes involved in tumor progression and angiogenesis." (PMID 34376784, 2021). "Specifically, the expression of RUNX1 in tumor initiating cells was seven times higher than that in the remaining tumor cells." (PMID 34359780, 2021). "They show that RUNX1 is necessary for driving blood vessel co-option from surrounding liver tissue and that regulation of this process relies on a signaling feedback loop between RUNX1 transcriptional target TSP1 in tumor cells and TGFβ1 in the liver." (PMID 34376784, 2021). "For example, several genes linked to RA credible SNPs in FLS were implicated in cell proliferation and tumor development (e.g., SPRED2, GRHL2, CDK6, RUNX1, and ZFP36L)." (PMID 34433485, 2021). "Overall, the total data indicated that RUNX1 contributed to the tumor growth by modulating miR-582-5p transcription." (PMID 33937021, 2021). "In this respect, these authors believed that hepatic RUNX1 has a tumor suppressor role inhibiting tissue angiogenesis." (PMID 34063472, 2021). "Taken together, miR-30d plays a tumor-suppressive role in resisting pancreatic tumorigenesis via a selective target loss of HK1 and SLC2A1-regulator RUNX1, subsequently resulting in inhibition of the Warburg effect." (PMID 34021267, 2021). "Runt domain transcription Factor 1 (RUNX1), an important tumor suppressor, is an important downstream molecule of the H19/miR-675 axis, and both H19 and miR-675 decrease RUNX1 expression." (PMID 34977037, 2021). "In particular, CASC2 exerts its tumor-suppressor function sponging miR-18a-5p and consequently promoting RUNX1, a tumor growth inhibitor in different cancers." (PMID 33503876, 2021). "Through the analysis of patient data in GEPIA, this study verified that RUNX1 is highly expressed in GBM tumor tissues." (PMID 34895074, 2021). "In conclusion, these findings indicated that miR-21 promotes tumor development by elevating the expression of RUNX1-mediated YAP." (PMID 33061847, 2020). "Here, we find that the nuclear PAK4 promotes osteoclastogenesis and tumor-induced osteolysis via phosphorylating RUNX1." (PMID 32549768, 2020). "Taken together, these data indicate that RUNX1 acts in both an oncogenic and a tumor suppressor mode in a context-dependent manner." (PMID 33353065, 2020). "Over-expression of RUNX1 in U87 GBM cells inhibited tumor growth by extensive down-regulation of target genes and deregulation of key developmental pathways." (PMID 32570879, 2020). "Three CpGs (cg04228935, cg11498607, and cg05000748) in the CpG island of RUNX1 showed significantly different methylation levels (Bonferroni corrected p < 0.05) between tumor and matched normal tissues obtained from 42 NSCLC patients." (PMID 32498288, 2020). "Tumour cells showed higher levels of apoptosis, lower proliferation rate and a greater sensitivity to PI3K inhibitors in vitro along as a decrease in tumour growth in xenografts models after ETV6/RUNX1 fusion gene abrogation." (PMID 31952221, 2020).